TRHR (thyrotropin releasing hormone receptor)
Description:
Receptor for thyrotropin-releasing hormone (TRH). Upon ligand binding, this G protein-coupled receptor triggers activation of the phosphatidylinositol (IP3)-calcium-protein kinase C (PKC) pathway.
Synonyms: TRH-R; CHNG7
Tractability: Small molecule: a drug acting on it is in phase 2 or 3 trials; it belongs to a druggable protein family. Antibody: UniProt places it where antibodies can reach, with high confidence; its Gene Ontology location is reachable by antibodies, with high confidence; UniProt predicts a signal peptide or a membrane-spanning region. PROTAC: a small molecule that binds it is known. Other modalities: an approved drug acts on it.
Target class: Peptide receptor (family A GPCR); Family A G protein-coupled receptor; Short peptide receptor (family A GPCR); Membrane receptor; Neuropeptide receptor
Gene: Protein-coding gene on chromosome 8 (109,086,585 to 109,121,565, forward strand). Ensembl gene ENSG00000174417.
Subcellular location: Cell membrane
Pathways (Reactome):
Signal Transduction: G alpha (q) signalling events; Peptide ligand-binding receptors
Gene Ontology:
Molecular function: protein binding; thyrotropin-releasing hormone receptor activity; G protein-coupled receptor activity
Biological process: G protein-coupled receptor signaling pathway; phospholipase C-activating G protein-coupled receptor signaling pathway
Cellular component: plasma membrane; membrane
Genetic constraint (gnomAD): Loss-of-function variants: 14 observed, 29.16 expected, observed/expected ratio (o/e) 0.48, 90% interval 0.32 to 0.75. The upper end of that interval is the gene's LOEUF score, 0.75, which puts it in group 3 of 6, group 1 being the genes least tolerant of losing a copy. Missense variants: 438 observed, 496.78 expected, observed/expected ratio (o/e) 0.88, 90% interval 0.81 to 0.95. Synonymous variants: 176 observed, 181.79 expected, observed/expected ratio (o/e) 0.97, 90% interval 0.86 to 1.1.
Homologues: Orthologues: chimpanzee TRHR (99% identical), macaque TRHR (99% identical), dog TRHR (97% identical), pig TRHR (96% identical), rabbit TRHR (96% identical), rat Trhr (94% identical), guinea pig TRHR (94% identical), mouse Trhr (93% identical), tropical clawed frog trhr (80% identical), zebrafish trhrb (65% identical), zebrafish trhra (63% identical). Paralogues in human: NMUR2 (27% identical), NMUR1 (27% identical), MLNR (23% identical), GHSR (23% identical), NTSR1 (22% identical), BRS3 (20% identical), EDNRB (20% identical), GRPR (20% identical), EDNRA (19% identical), NTSR2 (19% identical), NMBR (18% identical), GPR39 (17% identical), and 3 more.
Diseases named in the same sentence as TRHR in open-access papers:
TRHR is named in the same sentence as 30 diseases in open-access papers, as found by Europe PMC text mining. Sharing a sentence is not in itself a finding about the gene and the disease. The quoted sentences say what the papers report.
sarcopenia (6 papers, 2020 to 2025). Progressive decline in muscle mass due to aging which results in decreased functional capacity of muscles. "The TRHR rs7832552 SNP was found to play a notable role, with individuals carrying the C allele exhibiting a 2.6 times higher risk of sarcopenia than the risk in those with the TT genotype." (PMID 40428823, 2025). "This study analyzed 24 SNPs but found that only 4 SNPs (FTO rs9939609, ESR1 rs4870044, NOS3 rs1799983, and TRHR rs7832552) were significantly associated with sarcopenia." (PMID 40428823, 2025). "In the current study, TRHR rs7832552 C-allele carriers were at over 2-fold higher risk compared to TT homozygotes for sarcopenia defined according to the SMI." (PMID 32076017, 2020). "Polymorphisms in TRHR have been associated with sarcopenia, an age-related disorder characterized by muscle atrophy and functional decline, although its specific regulatory mechanism remains unclear." (PMID 41472177, 2025). "Several studies have associated single-nucleotide polymorphisms (SNPs) with muscle mass and strength in the elderly, and recently our group found that sarcopenia in elderly women was associated with polymorphisms in FTO, TRHR, ESR1, and NOS3." (PMID 34768452, 2021). "It should be noted that the SNPs showing associations in the present study (ACTN3 rs1815739, MTHFR rs1801131, and MTHFR rs1537516) are different from our previous study that identified associations of FTO, TRHR, ESR1, and NOS3 gene variants with sarcopenia." (PMID 34768452, 2021). "Four SNPs were associated with the %SMM and SMI definitions of sarcopenia; FTO rs9939609, ESR1 rs4870044, NOS3 rs1799983 and TRHR rs7832552." (PMID 32076017, 2020). "Other SNPs associating with sarcopenia include, fat mass and obesity associated gene (FTO) rs9939609 from fat, sex hormone Estrogen receptor 1 gene (ESR1) rs4870044, nitric oxide synthase 3 gene (NOS3) rs1799983 in the vascular endothelium, and Thyrotropin-releasing hormone receptor (TRHR) rs783255." (PMID 40772803, 2025). "The first three were associated with the %SMM definition, and TRHR rs7832552 with the SMI definition, but none were common to both sarcopenia definitions." (PMID 32076017, 2020).
Central hypothyroidism (5 papers, 2015 to 2017). A type of hypothyroidism due to an insufficient stimulation of an otherwise normal thyroid gland. "Isolated congenital central hypothyroidism (CeH) can result from mutations in TRHR, TSHB, and IGSF1, but its etiology often remains unexplained." (PMID 27603907, 2016). "Intriguingly, a female with a homozygous, nonsense TRHR mutation (p.R17*), was only diagnosed with central hypothyroidism following family screening at the age of 33, having previously achieved two normal pregnancies with subsequent lactation." (PMID 26416826, 2015). "Despite having been discovered only recently, this syndrome already encompasses more unique mutations and patients than all other known genetic causes of isolated central hypothyroidism combined (TSHB [12, –, 16] and TRHR)." (PMID 26840047, 2016). "Isolated central hypothyroidism is a rare entity, with an estimated incidence of 1:65 000 and known genetic causes affect the TSH biosynthetic pathway, comprising mutations in TSHB and TRHR, and IGSF1." (PMID 26416826, 2015). "Reports of families with TRHR or IGSF1 mutations also highlight the fact that family screening following diagnosis in a young proband, may identify apparently healthy first, second or third-generation family members with hitherto undiagnosed central hypothyroidism." (PMID 26416826, 2015). "Therefore, pituitaries harboring IGSF1 defects may not synthesize enough TRHR, leading to a type of central hypothyroidism combining low TSH synthesis and bioactivity." (PMID 28262687, 2017). "Direct sequencing of the coding exons and exon/intron boundaries of three candidate genes for central hypothyroidism (TSHB, CGA and TRHR) revealed no genetic abnormalities." (PMID 28262687, 2017).
hypothyroidism (4 papers, 2016 to 2022). Abnormally low levels of thyroid hormone. "It was also found that TCS caused hypothyroidism in rats through p38/TRHr-dependent pathway." (PMID 35721760, 2022). "TSH biopotency in our patient was not only reduced but also insensitive to TRH stimulation, which is consistent with our experimental findings that the ultimate molecular mechanism for hypothyroidism in this disorder is the decrease of TRHR expression." (PMID 28262687, 2017).
essential hypertension (2 papers, 2012 to 2021). Hypertension that presents without an identifiable cause. "In humans, a case-control study of 120 hypertensives and 63 normotensives indeed suggested that polymorphisms of the TRHR promoter were associated with essential hypertension." (PMID 22859963, 2012). "TRHR (thyrotropin releasing hormone receptor) is considered a potential biomarker of hypertension, but this gene might be associated with development of T1D in patients with hypertension." (PMID 33827531, 2021).
Obesity (2 papers, 2018 to 2025). Accumulation of substantial excess body fat. "Previous candidate gene studies on obesity and its related traits have reported GLP1R in European Americans, TRHR in Mexican-Mestizos and MMP1 in Koreans." (PMID 29868124, 2018).
adenoma (1 paper, 2024). A neoplasm arising from the epithelium. "Furthermore, in normal pituitary cells as in adenoma, endogenous TRH and TRH receptors (TRHR) were documented not only in thyrotroph but also in somatotroph cells." (PMID 38650008, 2024).
Anxiety (1 paper, 2017). Intense feelings of nervousness, tension, or panic often arise in response to interpersonal stresses. "Pathway analysis of the genes within these 4 ROH regions did not reveal relationships amongst those genes, but linked one of them (TRHR) to neurological diseases including seizures, anxiety, and neuronal hyperexcitability." (PMID 28358038, 2017). "Both the newly identified DPP4, previously linked to schizophrenia and brain dysfunction, and TRHR, previously linked to neuronal hyperexcitability, seizures, and anxiety may be linked to ASD in our cohort." (PMID 28358038, 2017).
hypopituitarism (1 paper, 2025). A condition of diminution or cessation of secretion of one or more hormones from the anterior pituitary gland. "There are many causative genes for its isolated form or for multihormonal hypopituitarism, such as TSHβ, TRHR, TBL1X and IRS4 (for heritable isolated central hypothyroidism) and PROP1, HESX1, SOX3 (for multihormonal hypopituitarism)." (PMID 39997750, 2025).
skin abnormalities (1 paper, 2013). "Indeed, as TRH receptor mutations have not been reported to cause skin abnormalities, it is certainly plausible that TRH may exert its wound healing-promoting effects via TRHR-independent mechanisms." (PMID 24023889, 2013).
thyroid cancer (1 paper, 2012). "Given the functional relationship between THRA, THRB, TSHR and TRHR, we decided to evaluate the combined effect of common genetic variants of these genes on thyroid cancer susceptibility." (PMID 23781307, 2012). "Here, our results suggest the importance of genetic variants in THRB in combination with polymorphisms in other genes of the thyroid function (i.e. TG or TRHR) in determining thyroid cancer risk." (PMID 23781307, 2012). "We found a gene–gene interaction of THRB with TG or TRHR for thyroid cancer susceptibility in the population studied." (PMID 23781307, 2012). "On the other hand, the genotyped THRB SNP that maps in the hormone binding domain (rs3752874) has shown a combined effect with either the TG-rs2076740 or the TRHR-rs4129682 for thyroid cancer risk, and the interaction effect was more than multiplicative (Pinteraction<0.05 and <0.01 respectively)." (PMID 23781307, 2012). "Our results confirm that THRA is a risk factor for DTC, and we show for the first time the combined effect of THRB and TG or TRHR on DTC susceptibility, supporting the importance of gene–gene interaction in thyroid cancer risk." (PMID 23781307, 2012).
TRHR also shares sentences with these, for which no sentence is quoted: Alzheimer disease (3 papers); cancer (3); Arthritis (1); central congenital hypothyroidism (1); central obesity (1); congenital hypothyroidism (1); E. coli infection (1); female infertility (1); Hypertension (1); kidney cancer (1); Macroorchidism (1); neuroendocrine tumors (1); neurological diseases (1); ovarian insufficiency (1); pancreatic cancer (1); pituitary adenomas (1); prostate carcinoma (1); schizophrenia (1); stomach cancers (1); tumor (1).